KRAS (KRas proto-oncogene, GTPase)
Diseases named in the same sentence as KRAS in open-access papers (continued):
Sharing a sentence is not in itself a finding about the gene and the disease.
lung adenocarcinoma (continued). "To address these questions, we conducted a comprehensive study in a large cohort of Chinese patients with lung adenocarcinoma and determined the associations between 5 common driver genes (EGFR, KRAS, ALK, RET, BRAF) and pathological subtypes, as well as their combined impact on prognosis." (PMID 29137260, 2017). "About 90% of KRAS mutations occur in exon 2 (codon 12 and 13), while exon 3 (codon 61) is less frequently involved; in never-smokers with lung adenocarcinoma, MUTKRAS is more frequently a transition (G to A) compared to transversion in current smokers." (PMID 26799287, 2017). "KrasG12A, KrasG12C, and KrasG12V—the next most frequent KRAS variants in lung adenocarcinoma in never-smokers after KRASG12D—were identified as moderate drivers of lung tumorigenesis, but were present in fewer tumors than KrasG12D." (PMID 29233960, 2017). "Importantly, we demonstrated a significant and also clinically relevant decrease in the OS of patients with KRAS-mutant lung adenocarcinoma and bone metastasis." (PMID 28051122, 2017). "Optimal treatment of KRAS-mutant lung adenocarcinoma remains an emerging field." (PMID 28716137, 2017). "Kirsten rat sarcoma viral oncogene homolog (KRAS) is the most common driver mutation in lung adenocarcinoma patients of non-Asian ethnicity." (PMID 28451792, 2017). "Blockade of PD-1/PD-L1 pathway may be a promising therapeutic strategy for human KRAS-mutant lung adenocarcinoma." (PMID 28451792, 2017). "Compellingly, a moderate up‐regulation of OTUB1 decreases the overall survival of lung adenocarcinoma patients with wt KRAS, suggesting that only medium levels of OTUB1 confers advantage to cancer cells and/or could affect their chemotherapeutic resistance." (PMID 26881969, 2016). "Notably, 17% of KRAS mutant lung adenocarcinomas harbour the G12D substitution (glycine to aspartic acid at position 12) which confers a more invasive tumour phenotype and a reduced response to anti-EGFR targeted therapies." (PMID 27933110, 2016). "We also found the substantial expression of several chemokines (CXCL1, CXCL5, CXCL8, and CX3CL1) related to cell migration, invasion, metastasis, or EMT, in KRAS-mutant lung adenocarcinoma cell lines, which was also dependent on MAPK signaling (unpublished data)." (PMID 27846317, 2016). "The inconsistency in PD-L1 expression among the KRAS-mutant lung adenocarcinoma cell lines may reflect their heterogeneity." (PMID 27846317, 2016). "Mutations in Kirsten rat sarcoma viral oncogene homolog (KRAS) are the most common mutations in lung adenocarcinomas, but currently, no targeted therapy is available." (PMID 27655296, 2016). "Other mutually exclusive genetic alterations, which have been reported to work as driver mutations in lung adenocarcinoma, include translocations of ALK, ROS1, RET, NTKR1, NRG2, ERBB4, and BRAF, and mutations of KRAS, BRAF, ERBB2, NRAS, HRAS, MAP2K1, NF1, and RIT1." (PMID 27005669, 2016). "Furthermore, the in vivo targeting of IMCs by the CCR1 inhibitor effectively suppressed tumour progression in vivo (Fig4) in a similar way to the targeting of TAMs in the oncogenic KRAS-induced lung adenocarcinoma model." (PMID 26183450, 2015). "Interestingly, most of these strongly staining RTKs were mutually exclusive, evoking the oncogenic driver mutations (EGFR, KRAS, ALK, and ROS1) observed in lung adenocarcinoma." (PMID 25989941, 2015). "GSE34914 includes RNA-seq data of tumor samples (no normal samples) from 16 lung adenocarcinoma patients with or without KRAS mutations (one transcriptome per patient)." (PMID 26356813, 2015).
lung adenocarcinoma (continued). "RAS and RAF oncogenes are amongst the best-characterised driver oncogenes and are mutated in a significant proportion of human cancers, notably pancreatic (∼90%) and lung adenocarcinoma (∼30%) in the case of KRAS, and melanomas (∼50%) and thyroid cancers (∼30%) in the case of BRAF." (PMID 26183450, 2015). "These targets are important in maintaining mutant KRAS lung adenocarcinomas suggesting that relieving some cellular anti-apoptosis restraints with SMAC mimetics may be effective in concert with some of these therapies." (PMID 26485762, 2015). "Given persistent uncertainty about the predictive value of KRAS MT status in NSCLC, we performed a retrospective, single-institution study to determine the relationship between KRAS MT and survival after platinum-based chemotherapy in patients with stage IV lung adenocarcinoma." (PMID 26471290, 2015). "No other mutated pairs of genes demonstrated a similarly negative association in lung adenocarcinoma, further arguing that the mutual exclusivity of KRAS and EGFR mutations is due to negative selection." (PMID 26047463, 2015). "A total of 1356 lung adenocarcinoma cases from April 2007 to May 2013 were sequenced for EGFR kinase domain mutations, KRAS mutations, HER2 kinase domain mutations, BRAF mutations, ALK fusions, ROS1 fusions, RET fusions and AKT1 mutations." (PMID 26486077, 2015). "In a randomized phase II study, it was demonstrated that a combination of selumetinib plus docetaxel significantly improved response rate and PFS when compared with docetaxel alone as second-line therapy for patients with KRAS mutant adenocarcinoma of the lung." (PMID 26410619, 2015). "Elevation of MAPK signaling was also observed in KRAS mutant lung adenocarcinoma cell lines." (PMID 26278961, 2015). "KRAS mutant adenocarcinoma represents a significant molecular cohort of lung adenocarcinoma." (PMID 26410619, 2015). "Whereas KRAS transitions mutations were more common in lung adenocarcinomas from patients without any smoking history." (PMID 26622815, 2015). "Therefore, screening for the EGFR and KRAS mutations, and ALK and KIF5B-RET translocations should be considered during initial diagnosis of lung adenocarcinomas." (PMID 26268359, 2015). "Taken together, our data suggest one-step screening platform for KIF5B-RET as well as EGFR, K-RAS, ALK oncogenic mutations be necessary for lung adenocarcinoma patients because EGFR or KRAS mutation are not infrequently found in KIF5B-RET-positive patients." (PMID 26268359, 2015). "Moreover, clinical studies that combine RET inhibitors and EGFR TKIs with other targeted drugs are warranted for the lung adenocarcinoma patients harboring concurrent KIF5B-RET fusion gene and EGFR or KRAS mutations." (PMID 26268359, 2015). "On the other hand, KRAS mutations have been detected in a significant proportion of never smoker lung adenocarcinoma patients, with an incidence up to 15%, and thus remain not rare in this subpopulation." (PMID 24729895, 2014). "We identified novel somatic mutations in EGFR/KRAS/ALK-negative lung adenocarcinoma in never-smokers and investigated the mutation frequency of altered genes." (PMID 24576404, 2014). "The somatic mutation profile in lung adenocarcinomas lacking targetable EGFR or KRAS mutations or ALK rearrangements in never-smokers is highly complex." (PMID 24576404, 2014). "Similarly, KRAS and STK11 mutations are less frequent in low TTP-expressing lung adenocarcinomas than in the high TTP-expressing cohort." (PMID 25541715, 2014).
lung adenocarcinoma (continued). "These mutations can co-exist with other known driver mutations in lung adenocarcinoma, including EGFR and KRAS and in the setting of acquired EGFR TKI resistance, suggesting that this may not be a driver mutation in itself." (PMID 25505733, 2014). "Taken together, EGFR and KRAS mutational status do not appear to be translated into a clearly distinctive and prominent expression signature in lung adenocarcinoma." (PMID 24205279, 2013). "In conclusion, in the present study, the clinicopathological characteristics and the spectra of EGFR and KRAS mutations in lung adenocarcinoma were different between never and heavy smokers." (PMID 24179496, 2013). "Epidermal growth factor receptor (EGFR) mutations are common in lung adenocarcinomas of never smokers, while KRAS mutations are more frequent among heavy smokers." (PMID 24179496, 2013). "The purpose of the present study was to elucidate the differences in the clinicopathological characteristics of EGFR- and KRAS-mutated lung adenocarcinomas and their related mutation spectra between never smokers and heavy smokers." (PMID 24179496, 2013). "The clinicopathological characteristics and the spectra of the EGFR and KRAS mutations in lung adenocarcinoma were different between the never and heavy smokers." (PMID 24179496, 2013). "In lung adenocarcinoma, the mutational spectrum is dominated by EGFR and KRAS mutations." (PMID 24205279, 2013). "Conversely, inhibition of PI3K pathway components like AKT without inhibition of RAS signaling is unlikely to be efficacious in triple negative breast cancers or lung adenocarcinomas, regardless of KRAS mutation status." (PMID 20591134, 2010). "Basically, mutations involving EGFR, ERBB2 and KRAS are mutually exclusive and are thought to represent early events in the carcinogenesis of lung adenocarcinoma in never (EGFR and ERBB2) and current smokers (KRAS)." (PMID 21532835, 2010). "Mutations observed in EGFR, KRAS, BRAF, and FGFR4 in lung adenocarcinomas." (PMID 17487277, 2007). "Nevertheless, these findings suggest that patients whose lung adenocarcinomas have KRAS mutations will not experience significant tumor regression with either drug." (PMID 15696205, 2005). "Our previous report revealed that the main group of non-TRU-type lung adenocarcinomas were hepatocyte nuclear factor 4α (HNF4α)-positive adenocarcinomas with gastrointestinal features that frequently harbored KRAS mutations and TTF-1 inactivating mutations/hypermethylation." (PMID 38710944, 2025). "Notably, some lung SCC samples exhibited mutations typically associated with lung adenocarcinoma or other non-squamous histology, such as KRAS, EGFR, and MET mutations." (PMID 41515905, 2025). "We speculate that this is not because of the higher frequency of HNF4α-positive cases in Caucasians, but because of the higher frequency of KRAS mutations in HNF4α-negative adenocarcinomas (mainly TRU-type lung adenocarcinomas) in Caucasians." (PMID 38710944, 2025). "High BLT2 expression is observed in human lung adenocarcinomas with KRAS mutations, whereas BLT2 inhibition, either pharmacologically or through genetic knockout, decreases lung tumor formation, IL-6 production, and airway inflammation in KRAS-mutant mouse models." (PMID 39806421, 2025). "While our study provides evidence using LUAD cells harboring KRAS or EGFR mutations and KRASG12D-driven lung adenocarcinoma, it would be valuable to investigate whether this mechanism occurs in other cancers with different oncogenic changes that consistently activate ERK." (PMID 40860160, 2025). "Based on The Cancer Genome Atlas data of 456 primary lung adenocarcinomas (mostly Caucasian cases), the frequency of KRAS mutations was not significantly higher in HNF4A-high cases (35.9%, 42/117 cases) than in HNF4A-low cases (29.5%, 100/339 cases) (p = 0.121) (Online resource 9)." (PMID 38710944, 2025).
lung adenocarcinoma (continued). "Our findings suggest that the EGFR mutation frequency was higher in women, non-smokers, lung adenocarcinoma, and the IA subtype in lung adenocarcinoma patients, while the KRAS mutation rate was higher in men and patients with longer tumor long diameter and lower in lung adenocarcinoma patients." (PMID 39364008, 2024). "Interestingly, a recent study showed that Kras oncogene ablation could prevent resistance to KRAS inhibitors in advanced lung adenocarcinomas, supporting the potential benefit of protein degradation." (PMID 39718828, 2024). "Most recently, it was reported that KRAS G12C mutation (but not other KRAS mutations or with no mutation in KRAS) significantly increased risk of disease recurrence in stage I surgically resected lung adenocarcinomas." (PMID 38884086, 2024). "Given the importance of tumor-intrinsic IFNγ signaling in sensitizing KPAR tumors to antitumor immune responses, the ability of oncogenic KRAS to suppress IFN pathway signaling may represent a major mechanism of immune evasion in KRAS-mutant lung adenocarcinoma." (PMID 38635884, 2024). "Indeed, oncogenic KRAS, closely related to lung adenocarcinoma development, induces an upregulation of the carrier SLC7A11 and, therefore, an increase in the intracellular concentration of cystine and cytoprotective glutathione in conditions of oxidative stress." (PMID 38539554, 2024). "Indeed, using a KRAS-driven lung adenocarcinoma mouse model wherein both KRAS-G12D and deregulated MYC expression can be conditionally activated, the researchers present compelling evidence demonstrating the collaboration between these two oncogenes to instruct an immunosuppressive TIME." (PMID 39164274, 2024). "Thus, patients with KRAS-mutant lung adenocarcinoma might be especially sensitive to anti-CD47 immunotherapy." (PMID 36413402, 2023). "Using the potent GR agonist, dexamethasone (DEX), we discovered GR agonists cause G1/S cell-cycle arrest via up-regulation of CDKN1C in responder NSCLC lines and that growth inhibition occurred in lung adenocarcinoma and squamous tumor lines with and without other oncogenic mutations such as KRAS." (PMID 37035141, 2023). "In support of this paradigm, KRAS mutations did not impart lower c-Scores in lung adenocarcinoma." (PMID 37558751, 2023). "Recent studies have identified gene expression changes triggered by KRAS mutations, and some studies have shown that KRAS mutations increase the expression of VEGFR1 and VEGFR2 in CRC and lung adenocarcinoma, but the mechanism of this association remains unclear." (PMID 36517805, 2022). "Another study of lung adenocarcinoma (LUAD) patients analyzed RNA expression and somatic mutation data from The Cancer Genome Atlas (n = 516) to assess the overall survival (OS) and disease-free survival (DFS) based on the abundance of KRAS transcript variants." (PMID 36393833, 2022). "KRAS/STK11 co-mutation might drive intrinsic resistance to PD-1/PD-L1 inhibitors, as it was the only marker associated with PD-L1 negativity among 924 intermediate/high TMB lung adenocarcinoma patients." (PMID 35251972, 2022). "From this, one might be tempted to conclude that lung adenocarcinomas lacking a KRAS mutation have acquired functionally similar patterns of signalling network activation to those with KRAS mutations." (PMID 36163168, 2022). "Moreover, our pharmacologic results suggest that targeting the upstream AMPK/CAMKK complex may offer therapeutic benefit to KRAS/LKB1 mutant lung adenocarcinoma patients." (PMID 33514834, 2021).
lung adenocarcinoma (continued). "Therefore, the inhibition of PKCι may be a rational approach to suppressing NSCLC, particularly in specific contexts such as mutant KRAS-expressing lung adenocarcinoma." (PMID 34073823, 2021). "Finally, the study completed single cell sequencing of tumor and normal lung tissue from two Stage 1A lung adenocarcinoma patients with KRAS activating mutations and validated the organoid findings that AT2 cells de-differentiate in early-stage lung adenocarcinoma." (PMID 33572297, 2021). "Interestingly, the BCAR4 fusion-positive patients showed the consistent features of being never-smokers, exhibiting absent or rare mutations of EGFR or KRAS genes and diagnosis with lung adenocarcinoma." (PMID 33204025, 2021). "In this regard, the group of Heymach took advantage of isogenic pairs of murine and human KRAS-driven lung adenocarcinoma cells (K tumors) with concomitant knockdown of LKB1 (KL tumors) and KEAP1 (KLK tumors) to explore the potential metabolic adaptations that might be targeted." (PMID 32443774, 2020). "To explore whether enhancing CD8+ T cell responses to mutant KRAS inhibits tumor growth, we used an inducible lung adenocarcinoma model in which expression of oncogenic KRAS-G12D is induced after intra-tracheal delivery of Cre expressing adenovirus, Adeno-Cre19." (PMID 33298945, 2020). "However, suppressive effect of AGTPBP1 expression on lung adenocarcinoma was suggested by the analysis of LUAD-TCGA datasets without considering KRAS mutation." (PMID 33276627, 2020). "In this study, the high incidence of coexisting KRAS and EGFR driver mutations and the lower than expected IDH1/2 VAF suggest that IDH1/2 mutations may be branching drivers promoting subclonal progression of lung adenocarcinomas." (PMID 32333643, 2020). "In addition, further studies are still required to study whether miR‐195 and LINC00461 expressions are associated with the presence of KRAS and EGFR in lung adenocarcinoma and to better elucidate the modulatory role of KRAS and EGFR in NSCLC." (PMID 31967713, 2020). "Although histological and immunohistochemical analyses have been accepted as the reference standard, identification of the relationship between DESCT quantitative measurements and KRAS status could help determine the molecular categories of lung adenocarcinoma." (PMID 31783917, 2019). "In addition, our model is unique as it can better represent human lung adenocarcinoma cases with no common KRAS and EGFR mutations." (PMID 29415661, 2018). "Interestingly, RUNX3 inactivation in KRAS driven lung adenocarcinoma has been shown to accelerate malignant progression and it will be of interest to test, whether RUNX interferes with YAP-FOS/AP1 co-operation in mediating EMT and malignant tumor progression." (PMID 29581836, 2018). "Since RANK expression correlated with the mutant KRas status, we tested whether pharmacologic blockade of RANKL/RANK would affect the in vivo growth of human KRAS mutant lung adenocarcinomas using one patient-derived xenograft (PDX) in immunocompromised NSG (NOD-scid IL2Rγnull) mice." (PMID 29118048, 2017). "Patient #071, who was diagnosed with lung adenocarcinoma, stage IV due to metastases to the brain, adrenal gland, and bone (multiple spines, pelvic bone, humerus, femur, and ribs), had 125 variants including EGFR mutations (L858R and T790M) and multiple KRAS mutations." (PMID 29290998, 2017). "The aim of our study was to analyze the mutational rate of EGFR, KRAS, BRAF, ERBB2 and PI3KCA in a large cohort of 2,219 unselected French patients presenting in routine clinical practice for first line treatment decision of metastatic or recurrent lung adenocarcinoma." (PMID 28881604, 2017).